MRGPRF (MAS related GPR family member F)
Description:
Orphan receptor. May bind to a neuropeptide and may regulate nociceptor function and/or development, including the sensation or modulation of pain (By similarity).
Synonyms: GPR140; GPR168; MRGF; MGC21621; RTA
Tractability: Small molecule: it belongs to a druggable protein family. Antibody: its Gene Ontology location is reachable by antibodies, with high confidence; UniProt places it where antibodies can reach, with medium confidence; UniProt predicts a signal peptide or a membrane-spanning region; the Human Protein Atlas places it where antibodies can reach.
Target class: Family A G protein-coupled receptor; Membrane receptor
Gene: Protein-coding gene on chromosome 11 (69,004,376 to 69,014,407, reverse strand). Ensembl gene ENSG00000172935.
Subcellular location: Cell membrane
Subcellular location (Human Protein Atlas): Plasma membrane; Vesicles; Nuclear membrane; Nucleoplasm; Primary cilium transition zone
Gene Ontology:
Molecular function: G protein-coupled receptor activity
Biological process: G protein-coupled receptor signaling pathway
Cellular component: plasma membrane; membrane
Genetic constraint (gnomAD): Loss-of-function variants: 6 observed, 7.78 expected, observed/expected ratio (o/e) 0.77, 90% interval 0.42 to 1.5. That is too few expected variants to judge how well the gene tolerates losing a copy. Missense variants: 500 observed, 417.17 expected, observed/expected ratio (o/e) 1.2, 90% interval 1.11 to 1.29. Synonymous variants: 242 observed, 188.4 expected, observed/expected ratio (o/e) 1.28, 90% interval 1.16 to 1.43.
Homologues: Orthologues: chimpanzee MRGPRF (99% identical), macaque MRGPRF (97% identical), pig MRGPRF (91% identical), dog MRGPRF (90% identical), guinea pig MRGPRF (87% identical), mouse Mrgprf (86% identical), rat Mrgprf (85% identical). Paralogues in human: MRGPRX2 (33% identical), MRGPRD (30% identical), MRGPRX1 (30% identical), MRGPRX4 (30% identical), MRGPRX3 (29% identical), MRGPRG (28% identical), MAS1 (28% identical), MRGPRE (27% identical), MAS1L (27% identical), GPR152 (20% identical).
Diseases named in the same sentence as MRGPRF in open-access papers:
MRGPRF is named in the same sentence as 13 diseases in open-access papers, as found by Europe PMC text mining. Sharing a sentence is not in itself a finding about the gene and the disease. The quoted sentences say what the papers report.
melanoma (3 papers, 2022 to 2025). A malignant, usually aggressive tumor composed of atypical, neoplastic melanocytes. "Mechanistically, USP45's catalytic domain directly binds to the N‐terminal of MRGPRF and stabilizes MRGPRF, likely by removing its K63‐linked ubiquitination in melanoma cells." (PMID 40788071, 2025). "Collectively, these findings demonstrate that USP45 enhances the stability of MRGPRF in melanoma cells, likely by eliminating its K63‐linked ubiquitination." (PMID 40788071, 2025). "USP45 acts as a melanoma suppressor by stabilizing MRGPRF, which weakens the PI3K/AKT pathway, suppresses tumor growth, and reduces melanoma cell migration and invasion." (PMID 40788071, 2025). "Collectively, these observations demonstrate that USP45 acts as a suppressor of melanoma, possibly by stabilizing MRGPRF." (PMID 40788071, 2025). "It is possible that the promoter of USP45, like that of MRGPRF, is hypermethylated, leading to decreased expression in melanoma." (PMID 40788071, 2025). "Among these, MRGPRF is a newly identified melanoma suppressor whose expression is downregulated in melanoma." (PMID 40788071, 2025). "To delineate the mechanism by which USP45 stabilizes MRGPRF in melanoma cells, we treated A375 and SK‐MEL‐2 cells with protein synthesis inhibitor CHX and proteasome inhibitor MG132." (PMID 40788071, 2025). "We also found that MrgprF is markedly decreased in advanced stage melanoma, compared to common melanocytic nevi (CMN) and primary melanoma, by analyzing whole genome oligo-microarray datasets." (PMID 35504869, 2022). "We found that forced expression of highly conserved mouse MrgprF (mMrgprF) in B16, a mouse melanoma cell line, significantly inhibited the formation of lung metastasis, visualized by a dramatic decrease in tumor number compared to the control group." (PMID 35504869, 2022). "Supporting this theory, we observed that USP45 affects the stability of MRGPRF protein, indicating that a dysregulated ubiquitin–proteasome system may also contribute to reduced MRGPRF expression and melanoma tumorigenesis." (PMID 40788071, 2025). "Notably, although both USP45 and MRGPRF play critical roles in controlling melanoma development, their functions in melanocytes, the cells from which melanoma originates, remain undetermined." (PMID 40788071, 2025). "This could offer a more extensive comprehension of the molecular pathways that regulate the stability and activity of MRGPRF in melanoma cells." (PMID 40788071, 2025). "Additionally, we investigated the mechanism that governs the interaction between USP45 and MRGPRF in melanoma." (PMID 40788071, 2025). "MRGPRF is a novel melanoma suppressor that inhibits the PI3K/AKT pathway." (PMID 40788071, 2025). "Furthermore, we revealed that MrgprF low expression positively correlates with RAS and BRAF mutations in the CCLE melanoma dataset." (PMID 35504869, 2022). "However, the regulation of MRGPRF in melanoma remains unclear." (PMID 40788071, 2025). "Given that both USP45 and MRGPRF repress melanoma and that USP45 stabilizes MRGPRF, we investigated whether MRGPRF acts downstream of USP45 in inhibiting melanoma." (PMID 40788071, 2025). "To investigate whether USPs influence the proteostasis of MRGPRF, thereby regulating melanoma tumorigenesis, we initially screened 40 USPs that may influence the stability of MRGPRF and identified USP45 as a potent stabilizer of MRGPRF." (PMID 40788071, 2025). "In summary, our data demonstrate that USP45 functions as a melanoma suppressor, at least in part, by stabilizing MRGPRF, thereby attenuating the PI3K/AKT pathway, inhibiting proliferation, inducing cell cycle arrest, promoting apoptosis, and mitigating the migration and invasion of melanoma cells." (PMID 40788071, 2025). "Whether the antimelanoma effect of USP45 is mediated by MRGPRF in these xenograft tumors, and whether USP45 overexpression represses melanoma metastasis, has not been tested." (PMID 40788071, 2025).
cutaneous melanoma (2 papers, 2022 to 2024). A primary melanoma arising from atypical melanocytes in the skin. "Recently, it has been reported that MrgprF (GPR168) acts as a tumor suppressor in cutaneous melanoma by restraining Akt signaling." (PMID 38805406, 2024). "Taken together, our findings suggest that MrgprF, a novel tumor suppressor in cutaneous melanoma, may be useful as a therapeutic target in the future." (PMID 35504869, 2022). "In this study, we identify that MrgprF, a MAS related GPR family member, is decreased in cutaneous melanoma tissues and cell lines due to hypermethylation of its promoter region, and show that patients with CM expressing high levels of MrgprF exhibit an improved clinical outcome." (PMID 35504869, 2022).
chronic myelogenous leukaemia (1 paper, 2020). "PE‐Ima (LIF, MRGPRF, GRM3, TNNI1 and CACNA2D1) predicted imatinib response in chronic myelogenous leukaemia patients." (PMID 34766125, 2020).
cancer (5 papers, 2015 to 2025). A tumor composed of atypical neoplastic, often pleomorphic cells that invade other tissues. "There are few studies on WD repeat domain 86 (WDR86) and MAS related GPR family member F (MRGPRF) in cancer." (PMID 35132081, 2022). "Most genes presented a rising tendency in different cancer types, like MRGPRF in BLCA." (PMID 40478912, 2025). "Therefore, we decided to uncover the functional roles of MrgprF in CM by determining its molecular mechanism, and screen for potential anti-cancer compounds targeting MrgprF." (PMID 35504869, 2022). "The results of methylation analysis further expanded our understanding of CEDGs expression, explaining the decreased expression of some CEDG in a certain cancer type, like ALDH3B1 in LUSC and MRGPRF in UCEC." (PMID 40478912, 2025). "Most of CEDGs like CCND1, ALDH3B1, MYEOV were frequently hypomethylated in cancer, while FGF3, FGF4, MRGPRF and CPT1A were hypermethylated in most cancers." (PMID 40478912, 2025).
tumor (4 papers, 2022 to 2024). "On the contrary, MrgprF knockdown promotes tumor cell proliferation and transformation of immortalized human keratinocyte-HaCaT cells, supporting the inhibitory role of MrgprF during tumor progression." (PMID 35504869, 2022). "As expected, we observed subcutaneous tumors in the vector control group, while the MrgprF overexpression group robustly retarded tumor growth in vivo, with decreased tumor weights and volumes compared to control group." (PMID 35504869, 2022). "Male nude mice were randomly divided into two groups, MrgprF overexpressing and control cell lines were subcutaneously injected (1 × 106 cells/point), and the tumor growth was measured every 4 days." (PMID 35504869, 2022). "Based on the functional role of MrgprF in regulating tumor cell migration in vitro, we used a lung metastasis mouse model to assess the effect of MrgprF overexpression in vivo." (PMID 35504869, 2022). "We demonstrate that MrgprF forced expression inhibits tumor cell proliferation, migration, xenograft tumor growth, and metastasis." (PMID 35504869, 2022). "To examine the potential role of MrgprF in regulating tumor cell migration, we performed wound healing and trans-well assays." (PMID 35504869, 2022). "Collectively, our findings identify MrgprF as a new tumor suppressor in CM." (PMID 35504869, 2022). "To determine the function of MrgprF in vivo, we performed a xenograft tumor formation assay." (PMID 35504869, 2022). "The endogenous MrgprF and p110γ interaction were confirmed in CM and other types of tumor cells." (PMID 35504869, 2022). "Importantly, we have provided evidence showing that MrgprF knockdown in HaCaT cells promotes their metastatic transformation and xenograft tumor growth." (PMID 35504869, 2022). "Importantly, MrgprF depletion promoted the transformation and xenograft tumor formation abilities of immortalized human keratinocyte-HaCaT cells." (PMID 35504869, 2022). "We showed that overexpression of MrgprF inhibited tumor cell growth compared to the control cells." (PMID 35504869, 2022). "In addition, AMG 706, a previously documented inhibitor for endothelial cell proliferation, is identified as a potential agonist for MrgprF, and can impede tumor growth both in vitro and in vivo." (PMID 35504869, 2022). "In addition, we found that AMG 706 treatment reduced tumor cell proliferation and migration abilities could be reversed by MrgprF knockdown, possibly via reducing DNMT3A and DNMT3B expression." (PMID 35504869, 2022).
MRGPRF also shares sentences with these, for which no sentence is quoted: Anxiety (1 paper); cervical cancer (1); glioblastoma (1); head and neck squamous cell carcinoma (1); metastatic tumor (1); oropharyngeal cancers (1); ovarian carcinoma (1); psychiatric disorder (1).